RNU6-1004P (RNA, U6 small nuclear 1004, pseudogene)
Gene: Small nuclear RNA gene on chromosome 12 (121,604,902 to 121,605,012, forward strand). Ensembl gene ENSG00000252393.
Homologues: Orthologues: chimpanzee U6 (99% identical), macaque U6 (87% identical), guinea pig U6 (68% identical), dog U6 (68% identical), rabbit U6 (68% identical), pig U6 (66% identical). Paralogues in human: RNU6-166P (75% identical), RNU6-1331P (74% identical), RNU6-15P (74% identical), RNU6-792P (74% identical), RNU6-1145P (73% identical), RNU6-26P (73% identical), RNU6-616P (73% identical), RNU6-665P (73% identical), RNU6-1 (72% identical), RNU6-1175P (72% identical), RNU6-11P (72% identical), RNU6-146P (72% identical), and 1286 more.